AUH (AU RNA binding methylglutaconyl-CoA hydratase)
Description:
Catalyzes the fifth step in the leucine degradation pathway, the reversible hydration of 3-methylglutaconyl-CoA (3-MG-CoA) to 3-hydroxy-3-methylglutaryl-CoA (HMG-CoA). Can catalyze the reverse reaction but at a much lower rate in vitro. HMG-CoA is then quickly degraded by another enzyme (such as HMG-CoA lyase) to give acetyl-CoA and acetoacetate. Uses other substrates such as (2E)-glutaconyl-CoA efficiently in vitro, and to a lesser extent 3-methylcrotonyl-CoA (3-methyl-(2E)-butenoyl-CoA), crotonyl-CoA ((2E)-butenoyl-CoA) and 3-hydroxybutanoyl-CoA (the missing carboxylate reduces affinity to the active site). Originally it was identified as an RNA-binding protein as it binds to AU-rich elements (AREs) in vitro. AREs direct rapid RNA degradation and mRNA deadenylation. Might have itaconyl-CoA hydratase activity, converting itaconyl-CoA into citramalyl-CoA in the C5-dicarboxylate catabolism pathway. The C5-dicarboxylate catabolism pathway is required to detoxify itaconate, an antimicrobial metabolite and immunomodulator produced by macrophages during certain infections, that can act as a vitamin B12-poisoning metabolite.
Tractability: Small molecule: it has a high-quality binding pocket. PROTAC: its protein half-life has been measured.
Gene: Protein-coding gene on chromosome 9 (91,213,815 to 91,361,961, reverse strand). Ensembl gene ENSG00000148090.
Subcellular location: Mitochondrion
Subcellular location (Human Protein Atlas): Cytosol; Centrosome; Vesicles
Pathways (Reactome):
Disease: 3-methylglutaconic aciduria
Metabolism: Branched-chain amino acid catabolism
Gene Ontology:
Molecular function: enoyl-CoA hydratase activity; methylglutaconyl-CoA hydratase activity; mRNA 3'-UTR binding; itaconyl-CoA hydratase activity; catalytic activity; RNA binding
Biological process: L-leucine catabolic process; fatty acid beta-oxidation; toxic metabolite repair; branched-chain amino acid catabolic process; L-amino acid catabolic process
Cellular component: mitochondrion; mitochondrial matrix
Genetic constraint (gnomAD): Loss-of-function variants: 27 observed, 37.46 expected, observed/expected ratio (o/e) 0.72, 90% interval 0.53 to 0.99. The upper end of that interval is the gene's LOEUF score, 0.99, which puts it in group 4 of 6, group 1 being the genes least tolerant of losing a copy. Missense variants: 448 observed, 412.74 expected, observed/expected ratio (o/e) 1.09, 90% interval 1 to 1.17. Synonymous variants: 174 observed, 152.43 expected, observed/expected ratio (o/e) 1.14, 90% interval 1.01 to 1.29.
Gene-disease validity (ClinGen):
ClinGen rates the evidence that AUH causes each of these diseases.
3-methylglutaconic aciduria type 1 (autosomal recessive): Definitive. 3-methylglutaconic aciduria (3-MGA) type I is an inborn error of leucine metabolism with a variable clinical phenotype ranging from mildly delayed speech to psychomotor retardation, coma, failure to thrive, metabolic acidosis and dystonia.
Homologues: Orthologues: chimpanzee AUH (99% identical), macaque AUH (98% identical), dog AUH (90% identical), pig AUH (90% identical), mouse Auh (87% identical), rat Auh (82% identical), rabbit AUH (76% identical), guinea pig AUH (73% identical), tropical clawed frog auh (65% identical), zebrafish auh (61% identical), Drosophila melanogaster CG8778 (48% identical), Caenorhabditis elegans ech-5 (42% identical), and 4 more. Paralogues in human: ECHDC2 (45% identical), ECHS1 (27% identical), HIBCH (23% identical), ECHDC3 (22% identical), ECH1 (22% identical), CDYL2 (22% identical), ECHDC1 (22% identical), ECI1 (22% identical), CDYL (21% identical), CDY1B (18% identical), CDY2A (18% identical), CDY2B (18% identical), and 1 more.
Diseases named in the same sentence as AUH in open-access papers:
AUH is named in the same sentence as 12 diseases in open-access papers, as found by Europe PMC text mining. Sharing a sentence is not in itself a finding about the gene and the disease. The quoted sentences say what the papers report.
3-methylglutaconic aciduria (2 papers, 2008 to 2019). A group of five inherited disorders caused by mutations in the AUH, DNAJC19, OPA3, and TAZ genes. "In conjunction with 3-methylglutaconic aciduria, which is a characteristic biochemical feature of the patients from this group, inspection of leucine degradation pathway showed moderately reduced expression of 3-methylglutaconyl-CoA hydratase gene, AUH." (PMID 18221507, 2008).
Organic aciduria (1 paper, 2020). "3-methylglutaconic aciduria type 1 (3-MGA-I) (MIM ID #250950) is an ultra-rare, autosomal recessive organic aciduria, resulting from mutated AUH gene, leading to the deficient 3-methylglutaconyl-CoA hydratase (3-MGH)." (PMID 33304818, 2020).
tumor (2 papers, 2019). "Some adhesion molecules play an important role in tumor recurrence, metastasis, and invasion.(Okegawa, Pong, Li, & Hsieh, 2004) Based on the construction of PPI network and module analysis, ACAA1, ACADSB, ALDH6A1, AUH, HADH,and PCCA with high degree of connectivity were selected as hub genes." (PMID 30793530, 2019).
AUH also shares sentences with these, for which no sentence is quoted: 3-methylglutaconic aciduria type 1 (3 papers); Alzheimer disease (1); Dihydropyrimidinase deficiency (1); dilated cardiomyopathy (1); heart failure (1); HLCS deficiency (1); inflammatory bowel disease (1); Intellectual disability (1); metabolic disorders (1).